PTPRG-AS1 (PTPRG antisense RNA 1)
Gene: Long non-coding RNA gene on chromosome 3 (62,214,400 to 62,369,406, reverse strand). Ensembl gene ENSG00000241472.
Diseases named in the same sentence as PTPRG-AS1 in open-access papers:
PTPRG-AS1 is named in the same sentence as 2 diseases in open-access papers, as found by Europe PMC text mining. Sharing a sentence is not in itself a finding about the gene and the disease. The quoted sentences say what the papers report.
cancer (1 paper, 2021). A tumor composed of atypical neoplastic, often pleomorphic cells that invade other tissues. "LncRNA PTPRG-AS1 (PTPRG-AS1) has been confirmed to function as a regulator in various cancers, whose function during HCC tumorigenesis is still not clear now." (PMID 34876904, 2021).
tumor (1 paper, 2021). "For instance, the lncRNA genes (LINC00324, PTPRGAS1 and SNHG17) have been related to ER+ and ER− subtypes, tumor histologic grade and clinic outcomes." (PMID 33902604, 2021).